GRHPR (glyoxylate and hydroxypyruvate reductase)
Description:
Enzyme with hydroxy-pyruvate reductase, glyoxylate reductase and D-glycerate dehydrogenase enzymatic activities. Reduces hydroxypyruvate to D-glycerate, glyoxylate to glycolate, oxidizes D-glycerate to hydroxypyruvate.
Synonyms: GLXR; PH2; GLYD
Tractability: Small molecule: a structure with a bound ligand is known; it has a high-quality binding pocket. PROTAC: ubiquitination databases record sites on it; its protein half-life has been measured.
Target class: Enzyme; Oxidoreductase
Gene: Protein-coding gene on chromosome 9 (37,422,664 to 37,437,259, forward strand). Ensembl gene ENSG00000137106.
Subcellular location (Human Protein Atlas): Cytosol; Nucleoplasm
Pathways (Reactome):
Metabolism: Glyoxylate metabolism and glycine degradation
Gene Ontology:
Molecular function: glyoxylate reductase (NADPH) activity; hydroxypyruvate reductase (NADH) activity; hydroxypyruvate reductase (NADPH) activity; hydroxypyruvate reductase [NAD(P)H] activity; NADPH binding; protein binding; protein homodimerization activity; carboxylic acid binding; glyoxylate reductase activity; NAD binding; NADP binding; oxidoreductase activity, acting on the CH-OH group of donors, NAD or NADP as acceptor
Biological process: glyoxylate metabolic process; dicarboxylic acid metabolic process
Cellular component: catalytic complex; cytoplasm; extracellular exosome; mitochondrion; cytosol; peroxisomal matrix
Genetic constraint (gnomAD): Loss-of-function variants: 26 observed, 27.48 expected, observed/expected ratio (o/e) 0.95, 90% interval 0.69 to 1.31. The upper end of that interval is the gene's LOEUF score, 1.31, which puts it in group 5 of 6, group 1 being the genes least tolerant of losing a copy. Missense variants: 349 observed, 395.96 expected, observed/expected ratio (o/e) 0.88, 90% interval 0.81 to 0.96. Synonymous variants: 171 observed, 168.79 expected, observed/expected ratio (o/e) 1.01, 90% interval 0.89 to 1.15.
Homologues: Orthologues: macaque GRHPR (95% identical), dog GRHPR (93% identical), rabbit GRHPR (90% identical), chimpanzee GRHPR (89% identical), pig GRHPR (89% identical), guinea pig GRHPR (87% identical), mouse Grhpr (86% identical), rat Grhpr (83% identical), tropical clawed frog grhpr.2 (72% identical), zebrafish grhpra (72% identical), Drosophila melanogaster CG1236 (53% identical), Drosophila melanogaster CG9331 (47% identical), and 4 more. Paralogues in human: PHGDH (28% identical), CTBP1 (27% identical), CTBP2 (27% identical).
Diseases named in the same sentence as GRHPR in open-access papers:
GRHPR is named in the same sentence as 20 diseases in open-access papers, as found by Europe PMC text mining. Sharing a sentence is not in itself a finding about the gene and the disease. The quoted sentences say what the papers report.
primary hyperoxaluria (12 papers, 2013 to 2025). A hereditary disorder characterized by excessive oxalate production, leading to hyperoxaluria. "Deletion of GRHPR underlies the gene defect in patients with primary hyperoxalurias Type II." (PMID 30025089, 2018). "Primary hyperoxaluria (PH) is an autosomal recessive disorder of oxalate metabolism caused by pathogenic variants in either of three genes (AGXT, GRHPR or HOGA1)." (PMID 36151119, 2022). "The 3 known genetic causes of primary hyperoxaluria (PH) are caused by mutations in AGXT (PH1), GRHPR (PH2), and HOGA1 (PH3)." (PMID 33898474, 2021). "For instance, primary hyperoxaluria is a disease caused primarily by mutations in GRHPR, a glyoxylate and hydroxypyruvate reductase, and its enzymatic activity requires homodimerization." (PMID 30573687, 2018). "Primary hyperoxaluria type II (PH II) results from the scarcity of hepatic enzyme glyoxylate reductase/hydroxypyruvate reductase (GRHPR) activity normally found in the cytosol." (PMID 23840917, 2013). "Primary hyperoxaluria (PH), a rare autosomal recessive disease of oxalate accumulation in the kidneys, is caused by biallelic pathogenic changes in three known genes: AGXT (PH1), GRHPR (PH2) and HOGA1 (PH3)." (PMID 40873808, 2025). "Primary hyperoxalurias type 2 (OMIM 260000) and type 3 (OMIM 613616) are respectively caused by a deficiency of glyoxylate reductase-hydroxypyruvate reductase (GRHPR) and 4-hydroxy-2-oxo-glutarate aldolase (HOGA) and each account for approximately 10 % of all primary hyperoxalurias." (PMID 26380104, 2015).
primary hyperoxaluria type 2 (10 papers, 2013 to 2026). "GRHPR (Glyoxylate reductase/hydroxypyruvate reductase) is an important enzyme in the glyoxylate cycle, and its deficiency can lead to primary hyperoxaluria type 2." (PMID 38406287, 2024). "Primary Hyperoxaluria type 2, a less severe form, is caused by a deficiency in glyoxylate reductase-hydroxypyruvate reductase (GRHPR), a primarily intrahepatic enzyme responsible for reduction of glyoxylate to glycolate and hydroxypyruvate to d-glycerate." (PMID 33678172, 2021). "A homozygous missense variation in exon 6 of the GRHPR gene (chr9:37 429 729 G>A) was identified in a 4-year-old female patient that substitutes glycine for aspartate at codon 165 (p.Gly165Asp) lead to hyperoxaluria primary type II (OMIM#260 000)." (PMID 41497027, 2026). "Primary Hyperoxaluria Type 2 (PH2), caused by mutations in the GRHPR gene, disrupts the normal metabolism of glyoxylate – metabolism characterized by overproduction of oxalate – leading to oxalate nephropathy." (PMID 41497027, 2026). "Primary hyperoxaluria type 2 (PH2) accounts for about 10% of PH cases and is due to mutations in the GRHPR gene on chromosome 10 which results in enzymatic dysfunction of glyoxalate reductase-hydroxypyruvate reductase (GRHPR)." (PMID 36833086, 2023). "Although GRHPR enzyme is predominantly expressed in the liver and isolated kidney transplantation is at risk of poor graft outcome, liver transplantation has not been reported in primary hyperoxaluria type 2." (PMID 26380104, 2015). "Primary hyperoxaluria type 2 (PH2; OMIM #260000 also known as L-glyceric aciduria) is less common than PH1 (exact incidence is unknown), and is characterized by a GRHPR enzyme defect." (PMID 28569194, 2017).
Hyperoxaluria (4 papers, 2022 to 2024). Increased excretion of oxalates in the urine. "WES analysis showed lower age group patients are prone to hyperoxaluria and harbor a predominant mutation c.494G>A in the GRHPR gene." (PMID 36619171, 2022). "As a result, the allelic shift from G to A for the GRHPR gene, rs180177314, can be anticipated as a risk factor for kidney stone formation and hyperoxaluria." (PMID 36619171, 2022). "Moreover, three genes, AGXT, HOGA1 and GRHPR with Novel variants known to cause hyperoxaluria were found frequently in the study cohort." (PMID 36619171, 2022). "Hyperoxaluria-related mutations were detected in nine patients (three AGXT defects, three GRHPR defects, and three HOGA1 defects), and calcium oxalate stones were found in eight of these patients as a result of stone sample evaluation." (PMID 37144129, 2023). "Both hyperoxaluric and non-hyperoxaluric patients were screened for sequence variations in known and candidate genes implicated in hyperoxaluria (AGXT, GRHPR, HOGA1, SLC26A1, SLC26A6, SLC26A7) by targeted next generation sequencing (tNGS)." (PMID 37270618, 2023). "To evaluate the contribution of genetic factors in the development of hyperoxaluria after bariatric surgery, we conducted tNGS to detect variations within genes known to cause monogenic hyperoxaluria and Ca-Ox-NL (AGXT, GRHPR, HOGA1; SLC26A1) as well as the candidate genes SLC26A6 and SLC26A7." (PMID 37270618, 2023).
glioma (1 paper, 2023). A benign or malignant brain and spinal cord tumor that arises from glial cells (astrocytes, oligodendrocytes, ependymal cells). "Then, through LASSO regression, 5 genes (ADD3, GRHPR, KLF13, RHBDL1 and SLC9A9) closely related to the prognosis of WHO Grade 4 glioma patients were selected." (PMID 37952042, 2023).
Headache (1 paper, 2025). Cephalgia, or pain sensed in various parts of the head, not confined to the area of distribution of any nerve. "The gene set for headache (ETFA, GRHPR, MMAB) was enriched in two primary functional clusters: one centered on core mitochondrial energy pathways, including ‘oxoacid metabolism’; and another related to molecular binding functions, such as ‘nucleoside phosphate binding’." (PMID 40943610, 2025). "Similarly, genes identified for headache (e.g., ETFA, GRHPR, MMAB) and facial pain (e.g., FASN, SPHK2) also consistently showed protective trends at both the expression and protein levels." (PMID 40943610, 2025).
lung adenocarcinoma (1 paper, 2024). A carcinoma that arises from the lung and is characterized by the presence of malignant glandular epithelial cells. "TCGA and GTEx database results showed significant differences in the expression of enzymes and transporters related to oxalate metabolism (LDHA, GRHPR, AGT, DAO, HAO2 and SLC26A1) in tumor tissues of lung adenocarcinoma patients." (PMID 38567154, 2024).
urolithiasis (1 paper, 2023). Stone(s) within the urinary tract. "A total of 82.8% of the patients in their cohort revealed urolithiasis and molecular diagnosis revealed 18 novel GRHPR gene mutations." (PMID 36409364, 2023).
tumor (9 papers, 2020 to 2026). "Conversely, lower GRHPR expression levels in tumors are associated with increased tumor cell proliferation and shorter patient survival." (PMID 39744494, 2025). "The mBc1 cluster expressed the pre-B cell receptor-associated molecule VPREB3, the B cell activation marker CD83, and genes associated with cell metabolism, cellular growth, and tumor progression (DDX54, PRDX6, GRHPR)." (PMID 36153593, 2022). "In tumor cell enriched regions, SHB, VRK2, KRT6A, GRHPR, CGA, SLC6A8, and LY6D were associated with the survival of NPC patients (P < 0.05)." (PMID 36618352, 2022). "While these findings suggest a potential relation between GRHPR loss and poor prognosis in HCC, further research is needed to elucidate whether GRHPR plays a functional role in tumour progression." (PMID 40943222, 2025). "The results showed that compared with normal tissues, the mRNA expression of five genes, ACBD5, ATAD1, DHRS4, GRHPR, and IDH1, was significantly up-regulated in tumor tissues." (PMID 38406287, 2024). "Compared to the normal liver tissues, 278 acetylation sites in 189 proteins were down-regulated while three acetylation sites in three proteins (EP300, GRHPR, and GLDC) were up-regulated with significant differences in tumor tissues." (PMID 33093847, 2020). "However, transcriptome expression profiling of the TCGA database CRC cohort revealed no significant differential expression of GRHPR between CRC and normal tissues, though its expression positively correlated with tumor purity." (PMID 41801343, 2026).
metabolic disorders (1 paper, 2024). "Those chronic disorders were related to metabolic disorders and congenital anomalies coded by AGTX, GALC, GRHPR, RDH12, and RPGRIP1L." (PMID 38553482, 2024).
GRHPR also shares sentences with these, for which no sentence is quoted: kidney stone (3 papers); breast carcinoma (1); chronic kidney disease (1); CNS lymphomas (1); genetic disorders (1); infection (1); liver abscesses (1); Nephropathy (1); osteogenesis imperfecta (1); primary hyperoxaluria type 1 (1); primary hyperoxaluria type 3 (1).